NRP2 (neuropilin 2)
Diseases named in the same sentence as NRP2 in open-access papers (continued):
Sharing a sentence is not in itself a finding about the gene and the disease.
colon carcinoma (9 papers, 2011 to 2025). "Further, an increased NRP1 expression has been found to increase the vessel number and cause poor prognosis, while increased expression of NRP2 stimulates tumor progression, and down-regulation of NRP2 expression inhibits colon cancer tumorigenesis." (PMID 40277760, 2025). "The majority of human primary and metastatic colon cancer cell lines expressed NRP-2 compared to the normal colonic mucosa." (PMID 35052853, 2022). "NRP-2 expression was shown to be higher in the majority of the human primary and metastatic colon cancer cell lines when compared to the normal colonic mucosa." (PMID 35052853, 2022). "Neuropilin-2 expression on colon cancer cell lines has been shown to enhance transforming growth factor-1 signaling, likely to result in Smad2/3 complex phosphorylation that persists." (PMID 35052853, 2022). "A previous study showed that NRP2, a transmembrane protein, can dissociate from the membrane to the cytoplasm in tongue cancer and colon cancer cells." (PMID 32983407, 2020). "Serum sample 30# was from a colon cancer patient, and the serum concentrations of Nrp1 and Nrp2 were 15 000 and 9956 pg/mL, which were 22.4‐ and 21.5‐fold the mean values for serum from normal human samples." (PMID 30758083, 2019). "In studies of human colon cancer cell line xenotransplantation, others demonstrated that the forced expression of Nrp2 increased tumor growth, whereas the knockdown of Nrp2 prevented tumor formation, or reduced tumor growth and increased apoptosis." (PMID 22948112, 2012). "These experiments provided evidence that NRP2 endows colon cancer cell lines for colony and xenograft formation." (PMID 21747928, 2011). "The expression of neuropilin-2 on colon cancer cell lines was indeed shown to promote transforming-growth factor-β1 signaling, leading to a constitutive phosphorylation of the Smad2/3 complex." (PMID 21747928, 2011). "The first investigations showed that NRP2 is expressed on human colon cancer cells while undetectable in uninvolved adjacent mucosa." (PMID 21747928, 2011). "Here, we used colon cancer cell lines transfected with NRP2 transgene or siRNA to investigate NRP2 involvement in EMT." (PMID 21747928, 2011). "A critical function in cancer cell survival was previously attributed to NRP2 in colon cancer cells." (PMID 21747928, 2011). "It has been reported that miR-331-3p could inhibit the proliferation and migration of colon cancer cells by targeting NRP2 (Neuropilin 2)." (PMID 37993925, 2023). "Moreover they showed that Nrp2 markedly enhances tumor formation in a colon cancer xenografts model." (PMID 22948112, 2012). "A role for NRP2 in cancer cells has been initially suggested in colon cancer." (PMID 21747928, 2011). "Moreover, NRP2 expression on colon cancer cell lines promoted their capacities to respond to TGF-β1." (PMID 21747928, 2011). "Co-immunoprecipitation experiment confirmed that NRP2 interacts with TGFRI in colon cancer cells." (PMID 21747928, 2011). "We showed that NRP2 promotes a constitutive Smad2/3 phosphorylation in colon cancer cell lines." (PMID 21747928, 2011). "In colon cancer, NRP1 expression correlates with increased vessel number and poor prognosis, while NRP2 over-expression stimulates tumor progression and the down-regulation of NRP2 expression inhibits tumorigenesis and increases apoptosis." (PMID 32766254, 2020). "NRP-2 is expressed in human colon cancer cells but not in unassociated nearby mucosa, according to early studies." (PMID 35052853, 2022). "To study the precise role of NRP2 in cancer progression, we decided to generate colon cancer cell lines expressing or not NRP2, using NRP2 gene transfer or NRP2 specific siRNA." (PMID 21747928, 2011). "We observed NRP2 expression at the membrane of 2 out of 3 colon cancer cell lines (SW620, Colo320 but not HT29)." (PMID 21747928, 2011). "Interestingly, we observed a reduced level of Smad7 in colon cancer cells following NRP2 gene transfer (data not shown)." (PMID 21747928, 2011).
COVID-19 (9 papers, 2021 to 2025). A disease caused by infection with severe acute respiratory syndrome coronavirus 2. "Proteins such as ACE2 co-receptors NRP2 may also be responsible for worsening the COVID-19 course although many mechanisms associated with Angiotensin I-converting enzyme type 2 (ACE2) can lead to increased SARS-CoV-2 virulence in diabetes mellitus." (PMID 39861420, 2025). "Despite organ-specific studies on ACE2 and other SARS-CoV-2 co-factors, detailed characterization of NRP1 and NRP2 expression in COVID-19-infected tissues remains limited." (PMID 41159753, 2025). "This study aims to provide a comprehensive assessment of NRP1 and NRP2 protein expression in the heart, lung, and hematolymphoid organs of COVID-19 autopsies using immunohistochemistry (IHC)." (PMID 41159753, 2025). "This study presents a detailed in situ analysis of Neuropilin 1 (NRP1) and Neuropilin 2 (NRP2) expression in fatal COVID-19 cases using immunohistochemistry and spatial multiplex immunofluorescence phenotyping, complemented by single cell RNA sequencing." (PMID 41159753, 2025). "This study presents a comprehensive analysis of NRP1 and NRP2 protein expression in COVID-19 in situ by IHC and CODEX, alongside transcriptomic data from publicly available scRNAseq data sets." (PMID 41159753, 2025). "It is possible that not only the cell tropism based on NRP1 and NRP2 expression contributes to the pathology of acute COVID-19 and PASC, but also the differential binding of neuropilins to proteolytic spike fragments." (PMID 41159753, 2025). "The role of NRP2 in COVID-19 pathophysiology has seldom been reported, though NRP2 can reportedly bind to the S protein." (PMID 37515185, 2023). "Both NRP1 and NRP2 were extracted in high concentrations from the lung tissue of deceased COVID-19 patients." (PMID 35021853, 2022). "NRP1 has another isoform, NRP2, whose function in COVID-19 has seldom been reported." (PMID 37515185, 2023). "NRP2 can bind to the S protein, but the role of NRP2 in COVID-19 has seldom been reported." (PMID 37515185, 2023). "Notably, whereas IL12RB1, NRP1 and NRP2 were only moderately increased as a function of viral load, CNTN1 expression was significantly correlated with viral load in these COVID-19 patients, an association that was more prominent in older patients." (PMID 35931765, 2022). "As macrophages and mast cells are critically involved in viral spreading, excessive cytokine storm, and fibrotic remodeling of infected tissue, modulation of these cells by targeting NRP2 might offer a new therapeutic strategy in acute COVID-19 as well as in PASC." (PMID 41159753, 2025). "Furthermore, NRP2 has potential as a target for novel therapeutics against COVID-19." (PMID 37515185, 2023). "Similar to the lung, macrophages and sinus histiocytes in the lymph nodes of COVID-19 autopsies were strongly positive for NRP1 and NRP2." (PMID 41159753, 2025). "Also in the lung, intussusceptive angiogenesis in COVID-19 has been demonstrated, accompanied by an upregulation of NRP1, NRP2, and VEGFA, in partial agreement with our own findings of NRP1 and NRP2 protein and transcript expression in the lung." (PMID 41159753, 2025). "NRP1 and NRP2 proteins were heterogeneously expressed in larger vessel EC of the trachea and lung of COVID-19 patients, while absent from small capillaries." (PMID 41159753, 2025). "The contribution of mdig-dependent expression of NRP1, NRP2 and genes in inflammation and glycosylation, to the pathogenesis of COVID-19 does not challenge the fact that ACE2 is the main receptor of SARS-CoV-2." (PMID 34335974, 2021). "Thus, NRP2 affects SARS-CoV-2 proliferation in coordination with NRP1 and ACE2 under inflammatory conditions and may serve as a novel therapeutic target for COVID-19 treatment." (PMID 37515185, 2023).
COVID-19 (continued). "Interestingly, when comparing relative expression patterns in the brain of healthy individuals vs. patients that died from COVID-19, we observed significant differences in the expression of the spike binding partners, such as upregulation of ILRAPL2 or NRP2 in discrete cell types." (PMID 35931765, 2022). "Thus, it is plausible to speculate that mdig dependent expression of NRP1 and NRP2 can enhance the infectivity of SARS-CoV-2, leading to the worsening effect of environmental exposure on the severity of COVID-19." (PMID 34335974, 2021).
triple-negative breast carcinoma (9 papers, 2013 to 2025). An invasive breast carcinoma which is negative for expression of estrogen receptor (ER), progesterone receptor (PR), and human epidermal growth factor receptor 2 (HER2). "LRP11 has been shown to drive tumor cell proliferation and metastasis in triple-negative breast cancer via the miR-149-3p/NRP2 axis, and its upregulation here correlates with the observed migratory phenotype." (PMID 40416783, 2025). "Anti-Nrp2 antibody treatment inhibited the growth of human triple negative breast cancer cells in immunocompromised mice, impeding an autocrine feedback loop of Nrp2/α6β1/GLI1/BMI-1." (PMID 38592275, 2024). "Vascular endothelial growth factor (VEGF)/neuropilin-2 (NRP2)/GLI family zinc finger 1 (GLI1) signaling suppressed ESRP1 expression via transcription repressor polycomb complex protein BMI1 in triple-negative breast cancer cell lines." (PMID 38110955, 2023). "In this work, we explored the relationships among LRP11-AS1, miR-149-3p and NRP2 in triple negative breast cancer cells." (PMID 35279146, 2022). "In addition, neuropilin-2 expression was suppressed in breast tumors, particularly in triple-negative breast cancers." (PMID 28418877, 2017). "In triple-negative breast cancer, α6β1 integrin binds to the VEGFR2–neuropilin 2 complex to promote FAK and ERK activation, thereby promoting the transcription of hedgehog signaling." (PMID 36911684, 2023).
epilepsy (8 papers, 2008 to 2025). A brain disorder characterized by episodes of abnormally increased neuronal discharge resulting in transient episodes of sensory or motor neurological dysfunction, or psychic dysfunction. "Together, our findings show that disruption of developmental Nrp2 regulation of interneuron circuit establishment, produces ASD-like behaviors and enhanced risk for epilepsy." (PMID 38405865, 2024). "Direct functional evidence for a function of semaphorins and their receptors in epilepsy is supported by Sema3F knockout mice and some NRP2 mutant mice that are more prone to seizures." (PMID 18781179, 2008). "Our studies using interneuron specific Nrp2 deletion combined with circuit and behavioral analyses support a role for developmental interneuronopathy in the co-occurrence of ASD related behaviors and risk for seizure disorders." (PMID 39578518, 2025). "This evidence is in line with several studies carried out in several experimental models of ASD-epilepsy (Cntnap2, En2, Fmr1, Nrp2), in which defects of GABAA receptor-mediated neurotransmission have been related to the pathogenesis of ASD-epilepsy comorbidity." (PMID 37153775, 2023). "However, a role for Nrp2 (or Sema3F) in human epilepsy is currently unknown." (PMID 39578518, 2025). "While clinical studies have identified Nrp2 polymorphisms in patients with ASD, whether dysregulation of Nrp2-dependent interneuron migration contributes to pathogenesis of ASD and epilepsy has not been tested." (PMID 38405865, 2024). "However, whether selective deletion of Nrp2 in interneurons alone and during their time of migration to the cortex and hippocampus could result in ASD/epilepsy phenotypes is currently not known." (PMID 38405865, 2024).
breast tumor (7 papers, 2013 to 2022). "The neurogenes HRH1 and NRP2 were upregulated in basal-related breast tumors and CD44+ cancer cells and another, STX1A, was upregulated in luminal B and HER2-enriched tumors." (PMID 26673618, 2016). "To investigate the role of NRP2 in TICs and its relationship to α6β1 further, we used primary tumour cells isolated from freshly resected breast tumour biopsies." (PMID 23436775, 2013). "Approximately 10% of SUM1315 cells exhibit high NRP2 expression, which is similar to the frequency observed in freshly isolated breast tumour cells." (PMID 23436775, 2013). "For example, studies in a wide range of breast tumors have shown that NRP1 and NRP2 are both expressed on almost all endothelial cells, but very rarely on breast tumor cells." (PMID 23667446, 2013). "The relationship between NRP2 and BMI-1 was further confirmed using NRP2high and NRP2low sorted populations from freshly isolated breast tumours." (PMID 23436775, 2013). "Interestingly, neuropilin 2 (NRP2) signaling increased GLI1 expression in breast tumor initiating cells, with GLI1 also inducing BMI-1, a key stem cell factor, and NRP2 expression, establishing an autocrine loop." (PMID 27689403, 2016). "To validate the existence of the proposed pathway in clinical specimens, we quantified the expression of VEGF, NRP2 and GLI1 in 32 TPN and 35 non-TPN human breast tumour specimens by qPCR." (PMID 23436775, 2013).
diabetes (7 papers, 2021 to 2025). "Concomitant upregulation of SEMA3A and NRP2 demonstrated in the present analysis indicates that diabetes induces M2-like macrophages through an autocrine mechanism." (PMID 34222276, 2021).
hepatocellular carcinoma (7 papers, 2015 to 2025). A malignant tumor that arises from hepatocytes. "A previous study by Wittmann and colleagues demonstrated that NRP2 expression is associated with increased motility of liver carcinoma cells." (PMID 34239847, 2021). "In adults with hepatocellular carcinoma, NRP2 expression correlates with shorter disease-free survival and overall survival." (PMID 34239847, 2021). "High expression of NRP2 is associated with poor overall survival for PDAC and hepatocellular carcinoma patients." (PMID 34650983, 2021). "Moreover, high NRP2 expression was noted in de-differentiated tumors and mesenchymal hepatocellular carcinoma cell lines." (PMID 34239847, 2021). "Therefore, NRP-2 could serve as a biomarker of bad prognosis, and what is more, a potential target in treating hepatocellular carcinoma." (PMID 40430075, 2025). "CENPA could also activate downstream CCND1 and NRP2 by binding with the transcription factor YY1, thereby affecting the proliferation and invasion of hepatocellular carcinoma." (PMID 39620895, 2024).
lymph node metastasis (7 papers, 2009 to 2024). "We found that patients with high semaphorin-3F and low neuropilin-2 had a lower risk of occult lymph node metastasis than the ones who had low semaphorin-3F or high semaphorin-3F and high neuropilin-2." (PMID 35565388, 2022). "Both expressions of low SEMA3F and a high NRP2 were associated with an increased risk of occult lymph node metastases." (PMID 35565388, 2022). "Subgroup analyses were also performed after stratification for T stage (T2 and T3/4) and locoregional lymph node metastasis (Nneg and Npos) as well as a high expression of NRP2 or its variants." (PMID 33918816, 2021). "Furthermore, positive NRP2 expression was associated with the occurrence of lymph node metastases as well as lymphovascular invasion." (PMID 39232098, 2024). "The SEMA3F receptor NRP2 is associated with a higher likelihood of lymph node metastases." (PMID 39232098, 2024). "In contrast, positive NRP2 expression is associated with the presence of lymph node metastases." (PMID 39232098, 2024). "The result of multivariate analysis showed that tumors with low SEMA3F expression or high SEMA3F expression associated with high NRP2 expression had a more than 25-fold higher risk of occult lymph node metastasis than tumors with high SEMA3F and low NRP2 expression." (PMID 35565388, 2022). "Additionally, NRP2 expression is linked to a higher risk of lymph node metastases occurrence." (PMID 39232098, 2024). "Thus, hematogenous metastatic spread and the development of pulmonary metastases were associated with high expression of ANGPT2, F3, and TIE1, whereas lymphogenous metastatic spread and the development of lymph node metastases were associated with high expression of NRP2." (PMID 29017512, 2017). "Here, patients with positive NRP2 expression showed significantly more often lymph node metastases as well as lymphovascular invasion in the subgroup of patients with early (y)pT-stage (p((y)pN) = 0.024, p(L) = 0.019, Suppl." (PMID 39232098, 2024). "Comparing the results obtained with the patients of the TCGA with our sample, we can observe that predictive capacity of the transcriptional expression of the SEMA3F/NRP2 genes in detecting the presence of occult lymph node metastases was maintained." (PMID 35565388, 2022). "The aim of the present study is to analyze the predictive capacity of the transcriptional expression of SEMA3F and NRP2 in determining the presence of occult lymph node metastases in patients with HNSCC." (PMID 35565388, 2022). "The risk of occult lymph node metastasis was low for the group of patients with high SEMA3F/low NRP2 expression, while it was high for patients with low SEMA3F or high SEMA3F/high NRP2 expression." (PMID 35565388, 2022). "Studies have reported that the expression of VEGFR1 is an important predictor of lymph node metastasis, with one showing that NRP2 plays an important role in the regulation of VEGF-induced invasion and migration in vitro." (PMID 34917039, 2021). "Nrp2 expression was correlated with lymph node metastasis, VEGF-C expression, and cytoplasmic CXCR4 expression." (PMID 19580679, 2009). "Nrp2 expression was correlated with lymph node metastasis (p = 0.0389), VEGF-C expression (p < 0.001), and cytoplasmic CXCR4 expression (p < 0.001)." (PMID 19580679, 2009). "Nrp2 expression was significantly correlated with lymph node metastasis, VEGF-C expression, and cytoplasmic CXCR4 expression." (PMID 19580679, 2009). "Survival analysis was performed on 113 patients and the following variables were examined: Nrp2 expression, tumor size, lymph node metastasis, hormonal status, histological grade, VEGF-C expression, and cytoplasmic or nuclear CXCR4." (PMID 19580679, 2009). "Interestingly, we could show that patients with positive NRP2 expression have significantly more often lymph node metastases (p = 0.041)." (PMID 39232098, 2024). "Furthermore, NRP2 expression could be correlated with a higher rate of lymph node metastases." (PMID 39232098, 2024).
lymph node metastasis (continued). "Increased expression of NRP2 was found in invasive and TNBC and was correlated with lymph node metastasis." (PMID 35279146, 2022). "Lymph node metastasis, VEGF-C expression, cytoplasmic CXCR4 expression, and also Nrp2 expression as shown in this study (p = 0.0268) had significant prognostic value for OS." (PMID 19580679, 2009). "Consequently, the objective of this study was to assess NRP2 and its ligand SEMA3F as potential biomarkers for patient survival and their ability to predict lymph node metastases in esophageal adenocarcinoma." (PMID 39232098, 2024).